AP2A1 (adaptor related protein complex 2 subunit alpha 1)
Description:
Component of the adaptor protein complex 2 (AP-2). Adaptor protein complexes function in protein transport via transport vesicles in different membrane traffic pathways. Adaptor protein complexes are vesicle coat components and appear to be involved in cargo selection and vesicle formation. AP-2 is involved in clathrin-dependent endocytosis in which cargo proteins are incorporated into vesicles surrounded by clathrin (clathrin-coated vesicles, CCVs) which are destined for fusion with the early endosome. The clathrin lattice serves as a mechanical scaffold but is itself unable to bind directly to membrane components. Clathrin-associated adaptor protein (AP) complexes which can bind directly to both the clathrin lattice and to the lipid and protein components of membranes are considered to be the major clathrin adaptors contributing the CCV formation. AP-2 also serves as a cargo receptor to selectively sort the membrane proteins involved in receptor-mediated endocytosis. AP-2 seems to play a role in the recycling of synaptic vesicle membranes from the presynaptic surface. AP-2 recognizes Y-X-X-[FILMV] (Y-X-X-Phi) and [ED]-X-X-X-L- [LI] endocytosis signal motifs within the cytosolic tails of transmembrane cargo molecules. AP-2 may also play a role in maintaining normal post-endocytic trafficking through the ARF6-regulated, non-clathrin pathway. During long-term potentiation in hippocampal neurons, AP-2 is responsible for the endocytosis of ADAM10. The AP-2 alpha subunit binds polyphosphoinositide-containing lipids, positioning AP-2 on the membrane. The AP-2 alpha subunit acts via its C-terminal appendage domain as a scaffolding platform for endocytic accessory proteins. The AP-2 alpha and AP-2 sigma subunits are thought to contribute to the recognition of the [ED]-X-X-X-L-[LI] motif (By similarity).
Synonyms: ADTAA; CLAPA1; AP2-ALPHA
Tractability: Antibody: UniProt places it where antibodies can reach, with high confidence; its Gene Ontology location is reachable by antibodies, with high confidence. PROTAC: ubiquitination databases record sites on it; its protein half-life has been measured.
Gene: Protein-coding gene on chromosome 19 (49,766,990 to 49,807,114, forward strand). Ensembl gene ENSG00000196961.
Subcellular location: Cell membrane; Membrane, coated pit
Subcellular location (Human Protein Atlas): Vesicles
Pathways (Reactome):
Disease: Dengue Virus Attachment and Entry; Nef Mediated CD4 Down-regulation; Nef Mediated CD8 Down-regulation; Potential therapeutics for SARS
Signal Transduction: Retrograde neurotrophin signalling; WNT5A-dependent internalization of FZD2, FZD5 and ROR2; WNT5A-dependent internalization of FZD4
Developmental Biology: EPH-ephrin mediated repulsion of cells; Recycling pathway of L1
Transport of small molecules: LDL clearance; VLDLR internalisation and degradation
Vesicle-mediated transport: Cargo recognition for clathrin-mediated endocytosis; Clathrin-mediated endocytosis
Immune System: MHC class II antigen presentation
Neuronal System: Trafficking of GluR2-containing AMPA receptors
Gene Ontology:
Molecular function: clathrin adaptor activity; low-density lipoprotein particle receptor binding; protein binding; protein kinase binding
Biological process: clathrin-dependent endocytosis; negative regulation of hyaluronan biosynthetic process; endocytosis; Golgi to endosome transport; intracellular protein transport; postsynaptic neurotransmitter receptor internalization; vesicle-mediated transport; protein transport; synaptic vesicle endocytosis
Cellular component: AP-2 adaptor complex; membrane; plasma membrane; clathrin coat of trans-Golgi network vesicle; clathrin-coated endocytic vesicle; clathrin-coated endocytic vesicle membrane; cytoplasmic side of plasma membrane; cytosol; endocytic vesicle membrane; endolysosome membrane; clathrin adaptor complex; filopodium tip; glutamatergic synapse; membrane coat; postsynaptic endocytic zone; presynapse
Genetic constraint (gnomAD): Loss-of-function variants: 20 observed, 87.8 expected, observed/expected ratio (o/e) 0.23, 90% interval 0.16 to 0.33. The upper end of that interval is the gene's LOEUF score, 0.33, which puts it in group 1 of 6, group 1 being the genes least tolerant of losing a copy. Missense variants: 805 observed, 1,151.8 expected, observed/expected ratio (o/e) 0.7, 90% interval 0.66 to 0.74. Synonymous variants: 567 observed, 502.02 expected, observed/expected ratio (o/e) 1.13, 90% interval 1.05 to 1.21.
Homologues: Orthologues: chimpanzee AP2A1 (100% identical), dog AP2A1 (99% identical), pig AP2A1 (99% identical), mouse Ap2a1 (98% identical), macaque AP2A1 (98% identical), guinea pig AP2A1 (98% identical), rat Ap2a1 (96% identical), rabbit AP2A1 (96% identical), zebrafish ap2a1 (85% identical), tropical clawed frog ap2a1 (84% identical), Drosophila melanogaster AP-2alpha (67% identical), Caenorhabditis elegans apa-2 (63% identical). Paralogues in human: AP2A2 (82% identical), AP1G1 (23% identical), AP1G2 (22% identical), AP4E1 (21% identical).
Diseases named in the same sentence as AP2A1 in open-access papers:
AP2A1 is named in the same sentence as 15 diseases in open-access papers, as found by Europe PMC text mining. Sharing a sentence is not in itself a finding about the gene and the disease. The quoted sentences say what the papers report.
Alzheimer disease (5 papers, 2015 to 2024). A progressive, neurodegenerative disease characterized by loss of function and death of nerve cells in several areas of the brain leading to loss of cognitive function such as memory and language. "AP2A1 is a candidate biomarker gene among patients with ovarian cancer, pediatric medulloblastoma, and Alzheimer’s disease, suggesting that its aberrant expression can be pathological." (PMID 34565296, 2021). "A recent report indicates colocalization of AP2A1 with neurofibrillary tangles in AP2A1 and AP2A2 plasmid-transfected cultured cells, suggesting the involvement of AP2 proteins in etiology of late-onset Alzheimer’s disease." (PMID 38674386, 2024). "However, with or without AP2A1, AP2A2 aberrant expression is linked to Alzheimer’s disease and is specifically linked to obesity, coronary disease, chronic bronchitis and nicotine withdrawal, suggesting that α isoforms may have distinct roles in cells." (PMID 34565296, 2021).
epithelial ovarian cancer (1 paper, 2024). "In parallel, another research initiative underscored that a signature enriched with AP2A1 bore potential diagnostic merit for epithelial ovarian cancer." (PMID 39702158, 2024).
lung carcinoma (1 paper, 2020). "We overexpressed the AP2A1, a core component of AP2 complex that was highly expressed in tumor tissue of lung cancers, in A549 cells and added purified human IgGs to cell culturing media." (PMID 32580738, 2020). "Many new targets of IgGs in lung cancer were non-cell surface proteins, but we noticed that many targets of these IgGs were adaptor proteins, such as the AP-2 complex including AP2A1, AP2A2, AP2B1, AP2S1, and AP2M1." (PMID 32580738, 2020).
metastatic cancers (1 paper, 2023). A carcinoma which has spread from the original site of growth to another anatomic site. "Interestingly, the altered expression of ESR1 was associated with anti-cancer drug resistance, and non-coding events were identified in the regulatory hotspot of AP2A1 in various metastatic cancers." (PMID 38132440, 2023).
pancreatic cancer (1 paper, 2024). "For example, circEIF3I may act as a molecular scaffold, interacting with SMAD3 and AP2A1 to form a complex that facilitates SMAD3 transport to early endosomes, activating downstream TGF-β signaling and promoting pancreatic cancer progression." (PMID 38802795, 2024).
papillary thyroid cancer (1 paper, 2024). "Of significance, AP2A1, AP2B1 and AP2M1 were highly expressed in papillary thyroid cancer (PTC) with the more aggressive BRAF-like gene signature compared to RAS-like PTC, as well as in the independent PTC dataset GSE60542." (PMID 37921808, 2024).
thyroid cancer (1 paper, 2024). "Control experiments validated the impact of SAHA on NIS, TSHR, AP2A1 and PICALM mRNA in thyroid cancer cells." (PMID 37921808, 2024).
cancer (2 papers, 2021 to 2023). A tumor composed of atypical neoplastic, often pleomorphic cells that invade other tissues. "We obtained the following correlation values (and statistical significances) between ESR1 and AP2A1 in the cancer samples: COR(PTA) = 0.9607 (p-val = 0.03093), COR(PTB) = 0.970449 (p-val = 0.02955), and COR(CWM) = 0.958562 (p-val = 0.04144)." (PMID 38132440, 2023). "Because the AP2A1 is important in vesicle formation and intracellular membrane trafficking, our result indicates that cancer switched the type of estrogen influence on the intracellular transport phenomena." (PMID 38132440, 2023). "By contrast, in cancer, the expression of ESR1 oscillates in-phase with the expression of AP2A1, so that expressions of both genes go up or down simultaneously." (PMID 38132440, 2023). "A very similar behavior, except that it was not significantly regulated in any of the three cancer nodules, was exhibited by AP2A1 (ΔCOR(PTA→NOR) = 7.60, ΔCOR(PTB→NOR) = −7.02, ΔCOR(PTB→NOR) = −6.84)." (PMID 38132440, 2023). "The increased overall correlation of the ADCY6 and AP2A1 with all other genes from the “Endocrine and other factor-regulated calcium reabsorption” pathway in PTA, but the decrease in the other two cancer nodules, indicates substantially different gene networks." (PMID 38132440, 2023). "Both AP2A1 and AP2A2 were reported to confer resistance to erlotinib, an anti-cancer drug, in lung cancer cells; interact with Shc, an SH2-containing proto-oncogene involved in growth factor signaling in mammalian cancer cells; and function in hemopoietic stem cell development." (PMID 34565296, 2021). "Thus, while its expression synergisms with the ATP2B3 (ATPase, Ca++ transporting, plasma membrane 3) and KLK2 (kallikrein-related peptidase 2) in NOR are not modified by ccRCC, the antagonistic expression with the AP2A1 is switched to a synergistic one in all three cancer nodules." (PMID 38132440, 2023). "For instance, the significant expression antagonism (COR(NOR) = −0.96624, p = 0.0338) of AP2A1 (adaptor-related protein complex 2, alpha 1 subunit) with ESR1 in the normal tissue is switched into expression synergism in each of the three cancer nodules." (PMID 38132440, 2023). "Interestingly, unlike AP2A1, no reported correlation was found between AP2A2 and cancer." (PMID 34565296, 2021).
infection (2 papers, 2023). The state of being infected such as from the introduction of a foreign agent such as serum, vaccine, antigenic substance or organism. "Similar to CHC2-YFP and CLC1-GFP plants, clear colocalization (46%) was observed on the endocytic vesicles at the infection sites between AP2A1-GFP with FM4–64." (PMID 37398405, 2023).
tumor (2 papers, 2013 to 2020). "The IgGs were significantly increased in cells with AP2A1 overexpression, indicating the IgGs would be delivered into tumor cells in an AP2-dependent manner." (PMID 32580738, 2020).
AP2A1 also shares sentences with these, for which no sentence is quoted: colorectal cancer (1 paper); cystadenoma (1); Huntington disease (1); neurological diseases (1); tauopathies (1).